BRAF (B-Raf proto-oncogene, serine/threonine kinase)
Diseases named in the same sentence as BRAF in open-access papers (continued):
Sharing a sentence is not in itself a finding about the gene and the disease.
ovarian carcinoma (continued). "Importantly, the role of BRAF mutations seems negligible in the context of renal cell tumors, testicular germ cell tumors, as well as cervical, endometrial, and ovarian carcinomas, as per existing postulations." (PMID 40002790, 2025). "BRAF p.V600E, a missense point mutation, is found in approximately 6% of ovarian cancers." (PMID 37600581, 2023). "Through examining the total 75 samples, among whom 17 patients developed KRAS mutation and 26 were examined for BRAF mutation, it has been identified that BRAF mutation may lead to developing ovarian cancer in females." (PMID 36267655, 2022). "Only one case that had the BRAF mutation was in stage IIIc ovarian cancer." (PMID 31030485, 2019). "Similarly, a study in a large panel of ovarian cancer cell lines identified a link between K‐Ras/BRAF mutation status and resistance to the dual PI3K/mTOR inhibitor, PF‐04691502." (PMID 28544747, 2017). "BRAF mutations are commonly associated with low-grade ovarian carcinoma." (PMID 22235203, 2012). "KRAS and BRAF mutations are less common in high grade ovarian cancers." (PMID 19638206, 2009). "In contrast, somatic mutations of BRAF were identified in 5 (8.6%) out of 58 ovarian carcinomas." (PMID 19018267, 2008). "Thus, inactivation of ERK1/2 results in marked growth inhibition in ovarian carcinomas with mutations in KRAS or BRAF in comparison with only a modest effect on wild-type tumours." (PMID 19018267, 2008). "Therefore, CI-1040 has the potential to be developed into a drug for the treatment of ovarian carcinomas in patients with either KRAS or BRAF mutations." (PMID 19018267, 2008). "In addition, our observations have an important therapeutic implication in ovarian cancer patients with KRAS or BRAF mutations." (PMID 19018267, 2008). "Three ovarian cancer cell lines harboured either KRAS or BRAF mutations." (PMID 19018267, 2008). "SKOV3 and A2780 showed weak expression of ERK1/2.These results suggest that activation of ERK1/2 may depend on KRAS/BRAF mutation in ovarian cancer cells." (PMID 19018267, 2008). "Furthermore, they suggest that the CI-1040-induced phenotypes depend on the mutational status of KRAS and BRAF in ovarian cancers." (PMID 19018267, 2008). "Therefore, further studies are needed to clarify the effects of other BRAF mutations in ovarian cancer, and to completely describe the mutation profile of KRAS-BRAF signalling in established ovarian cancer cell lines." (PMID 19018267, 2008). "Genomic DNA from 15 ovarian cancer cell lines was screened for BRAF mutations in coding exons 1–18." (PMID 18060073, 2007). "It is known that BRAF mutations have been identified in certain types of ovarian cancer; however, mutations in the downstream effectors of B-Raf including MEK1 and MEK2 may also be important contributors of ovarian cancer tumorigenesis." (PMID 18060073, 2007). "For ovarian carcinoma, presence of the BRAF V600E mutation as the marker was detected from archival paraffin-embedded ovarian tissue collected at the time of diagnosis, during ctDNA monitoring, BRAF V600E associated with OC remained undetectable, aligning with remission." (PMID 41201657, 2025). "Therefore, detection of KRAS and BRAF mutations in ovarian cancers may identify patients who will benefit from CI-1040 therapy." (PMID 19018267, 2008). "While previous studies have identified genomic similarities between BOTs and other ovarian cancer types, including common mutations in KRAS and BRAF, the transcriptomic parallels we observed between BOTs and ECs represent a novel finding." (PMID 39840716, 2025). "The gene–pathway enrichment heatmap and DepMap analyses collectively emphasize ITGB1, TIMP3, and BRAF as central molecular hubs in ovarian cancer biology." (PMID 41294900, 2025). "Survival analysis of the TCGA ovarian cancer cohort revealed that higher expression levels of TIMP3, BRAF, and ITGB1 were significantly associated with poorer overall survival." (PMID 41294900, 2025).
ovarian carcinoma (continued). "Collectively, this study defines a core regulatory axis—miR-192-5p/ITGB1/TIMP3/BRAF—that underpins differences in ovarian cancer progression and patient survival." (PMID 41294900, 2025). "It determined the VAF of ovarian cancer‐related mutations KRAS‐G12R, NRAS‐G12C, and BRAF‐V600E in both tissue and blood samples (n = 77), discriminating cancer patients and healthy individuals with significant difference (p < 0.001)." (PMID 39903775, 2025). "Mutations in genes encoding the RAS-RAF-MEK-ERK pathway protein can be detected in ovarian cancer, and BRAF and MEK inhibitor combinations are more effective and safer for ovarian cancer, especially for low-grade serosal ovarian cancer." (PMID 39882448, 2024). "In a literature search, we found only two previous reports of ovarian cancer patients responding to a BRAF inhibitor monotherapy." (PMID 36967525, 2023). "In preclinical data on ovarian cancer, cell lines with KRAS or BRAF mutations experienced significant growth inhibition and apoptosis compared to wild-type cells." (PMID 35204549, 2022). "Histologic types of ovarian cancer have been associated with different genetic alternations and both KRAS and BRAF mutations have been found in low-grade serous ovarian cancer (LGSOC), 16 to 44% KRAS mutation and 2 to 20% BRAF mutation." (PMID 33801965, 2021). "When we compared the mutation of ovarian cancer to other mucin-producing tumors, they all have the same mutant genes which were KRAS and BRAF, but different in the percentage of mutation." (PMID 31030485, 2019). "Type I ovarian cancer, which includes low‐grade serous carcinoma, endometrioid carcinoma, clear cell carcinoma, and mucinous carcinoma, has been shown to exhibit KRAS, BRAF, PI3KCA, and PTEN mutations." (PMID 29797793, 2018). "Our model supported notion that the four molecules in the EGFR/HER2/KRAS/BRAF signaling pathway also produce the synergic effect, exerting their own effect on ovarian cancer progression." (PMID 26490766, 2015). "Serous (69.5 %) and mucinous (11.3 %) ovarian cancer had high proportions of low BRAF expression, while serous (63.6 %) and endometrioid (13.6 %) ovarian cancer exhibited high EGFR expression." (PMID 26490766, 2015). "The absence or weak staining of BRAF (Negative and weak staining in tumor cell cytoplasm was considered to be mutation BRAF) (P = 0.045) and high EGFR expression (P = 0.041) were associated with the ovarian cancer histotype." (PMID 26490766, 2015). "A previous study has shown that the MAPK pathways have a significant role in the development and differentiation of ovarian cancer caused by KRAS and BRAF mutations." (PMID 25202426, 2014). "Although mutations in PIK3CA, KRAS, PTEN, BRAF and ARID1A are uncommon in HGSOC, they are characteristic of other ovarian cancer subtypes." (PMID 23839242, 2013).
ovarian carcinoma (continued). "Additionally, the low frequency of KRAS mutation or BRAF mutations in type II ovarian carcinomas in the current and previous studies suggest that p-ERK expression may be affected by the other receptor tyrosine kinase regulation mechanisms (i.e., EGFR, Her2, etc.)." (PMID 23820584, 2013). "In ovarian cancer, KRAS mutation has been identified in 35% low-grade serous tumors and 33% of borderline tumors, whereas, BRAF mutations occur in 30% of low-grade serous carcinomas and 28% of borderline tumors." (PMID 19638206, 2009). "This study examined the status of KRAS and BRAF mutations, in relation to extracellular signal-regulated protein kinase (ERK) activation in 58 ovarian carcinomas to clarify the clinicopathological and prognostic significance of KRAS/BRAF mutations." (PMID 19018267, 2008). "A panel of ovarian cancer cell lines and primary cultures was first analysed for tumour mutation status in the KRAS and BRAF genes." (PMID 19018267, 2008). "In summary, we have shown that the phenotypic change in ovarian carcinomas in response to ERK1/2 inactivation depends on the mutational status of KRAS and BRAF." (PMID 19018267, 2008). "A panel of ovarian cancer cell lines and primary cultures of ovarian cancer were first analysed for KRAS and BRAF gene mutation status." (PMID 19018267, 2008). "Therefore, ovarian cancer patients with KRAS or BRAF mutations may benefit from CI-1040 treatment." (PMID 19018267, 2008). "Genes comprising the MAPK pathway, BRAF, MEK1 and MEK2, were systematically scanned for mutations in 15 ovarian cancer cell lines using bidirectional direct sequencing of all exons." (PMID 18060073, 2007). "As to BOTS, we investigated these tumors in the context of the mutational status of the BRAF oncogene, which was demonstrated to be crucial for borderline ovarian tumors but not ovarian cancers." (PMID 39456618, 2024). "Herein, 128 serous ovarian tumors were analyzed, including borderline ovarian tumors (BOTS) with (BOT.V600E) and without (BOT) the BRAF V600E mutation, low-grade (lg), and high-grade (hg) ovarian cancers (OvCa)." (PMID 39456618, 2024). "Interestingly, the mutation rates for commonly reported genes in ovarian cancer such as RB1, PTEN, PIK3CA, NRAS, KRAS, and BRAF were below 3% in the entire cohort." (PMID 33016563, 2021). "Mutations in KRAS and BRAF, which may activate the mTOR/PI3K/AKT pathway, are common in low-grade ovarian cancers (60 %) but rare in high-grade cancers." (PMID 24848881, 2014). "Interestingly, both responders of the ovarian cancer subset had a simultaneous MAPK pathway mutation (one each in KRAS and BRAF)." (PMID 24036443, 2013). "Furthermore, preclinical models have shown that in addition to BRAF mutations in low-grade tumors, Raf-1 isoform predominantly mediates ovarian cancer cell growth compared with Raf-A or B-Raf isoforms." (PMID 22235203, 2012). "Therefore, we recommend that in further clinical trials of MEK inhibitors for ovarian cancer, patients are stratified on the basis of KRAS/BRAF mutational status." (PMID 19018267, 2008). "BRAF sequence variations identified in ovarian cancer cell lines." (PMID 18060073, 2007).
ovarian carcinoma (continued). "The significance of these findings is that BRAF and MEK1/2 mutations may be more common than anticipated in ovarian cancer which could have important implications for treatment of patients with this disease and suggests potential new therapeutic avenues." (PMID 18060073, 2007). "The significance of these findings is that BRAF and MEK1/2 mutations may be more common than previously recognized in ovarian cancer, which could have important implications for the treatment of patients with ovarian cancer." (PMID 18060073, 2007). "The NSCLC tumor harbored an activating mutation of PIK3CA (p.E545K) and the papillary thyroid tumor harbored an activating mutation in BRAF (p.V600E); neither mutation was detected in the ovarian cancer tumor despite high-depth, sensitive targeted panel sequencing." (PMID 27245685, 2016). "Moreover, mutations in KRAS and BRAF, which may activate the mTOR/PI3K/AKT pathway, are common in low-grade ovarian cancers (60%)." (PMID 26075229, 2015). "Although the possibility that other downstream targets of BRAF are mutated in conventional high-grade ovarian carcinomas cannot be completely ruled out, it would appear that the development of high grade serous carcinomas involves a pathway distinct from the MAP kinase signaling pathway." (PMID 19638206, 2009). "However, its favourable therapeutic index and high selectivity may outweigh its shortcomings in KRAS and BRAF mutant ovarian cancer." (PMID 19018267, 2008). "Interestingly, simultaneous mutations of KRAS and BRAF did not occur in the tested ovarian carcinomas with the exception of one mucinous case." (PMID 19018267, 2008). "Our method also determined the VAF of ovarian cancer‐related sites (KRAS‐G12R, NRAS‐G12C, and BRAF‐V600E) in clinical tissue and blood samples, enabling the discrimination between ovarian cancer patients and healthy volunteers." (PMID 39903775, 2025). "Cancer cells elicit autophagy as a mechanism of resistance to BRAF/MEK inhibitors, as was demonstrated in brain and ovarian cancers." (PMID 35847840, 2022). "Among the molecular markers, HER2, KRAS, BRCA1, BRAF, and EGFR were independent and statistically significant prognostic factors for ovarian cancer patient outcomes." (PMID 26490766, 2015). "This difference in sensitivity to the RAS–RAF–MEK–ERK pathway between ovarian cancer and the latter types is intriguing, and it probably reflects organ-specific roles of the KRAS and BRAF oncogenes." (PMID 19018267, 2008). "This difference in prognostic significance between ovarian cancer and the latter types is intriguing, and it probably reflects organ-specific roles of the KRAS/BRAF pathway." (PMID 19018267, 2008). "Our results underscore the importance that further characterization of the sensitivity of various BRAF and MEK mutants to small molecule inhibition is an important avenue to pursue towards the development of effective treatments for ovarian cancer." (PMID 18060073, 2007). "Both Grisham and Moujaber reported that for high-grade ovarian cancer, there is a loss rather than a gain of the BRAF and/or KRAS mutations, while low-grade ovarian cancers are predominantly characterized by these mutations." (PMID 38391958, 2024). "The opposite situation was observed for women bearing ovarian cancer with mutations in KRAS and/or BRAF who had better prognosis than those without them." (PMID 38391958, 2024). "A study including 140 patients (breast, cervical, endometrial, and ovarian cancers) from phase I program treated with PI3K/AKT/mTOR inhibitors, measured different potential biomarkers (PIK3CA, KRAS, NRAS, and BRAF) to see if a correlation was possible with the response rate of patients." (PMID 28008141, 2017).
ovarian carcinoma (continued). "Of note, no ovarian cancer patients within any stratum exhibited ALK rearrangement, BRAF, EGFR, or KIT mutations." (PMID 25593979, 2014). "The cell lines did not harbor the most commonly reported KRAS or BRAF mutations nor the most common BRCA1 and BRCA2 mutations identified in the French Canadian breast and ovarian cancer families." (PMID 22931248, 2012). "Finally, different molecular markers have low or high expression in Type I vs. Type II ovarian carcinomas, but are rarely totally expressed (PTEN mutation, PIK3CA, KRAS mutation, BRAF mutation) or totally absent in either Type I or Type II EOCs." (PMID 31973035, 2020). "Thus, the MAPK/BRAF/MEK pathway can be a target in both high-grade and low-grade ovarian cancer." (PMID 22235203, 2012).